CD274 (CD274 molecule)
Diseases named in the same sentence as CD274 in open-access papers (continued):
Sharing a sentence is not in itself a finding about the gene and the disease.
tumor (continued). "Lastly, we found a correlation between the hydra-identified tumor microenvironment subtype and CD274 and CTLA4 expression." (PMID 32275708, 2020). "It has been observed not only a reduction in tumor volume, but also a higher expression of CD274 (PD-L1), a transmembrane protein responsible for suppressing the immune response through T cell presence in the tumor of trained animals." (PMID 33613297, 2020). "Her tumor was also positive for Sig3, and OncoPanel sequencing revealed high-level genomic amplifications in CD274 (PD-L1) and PDCD1LG2 (PD-L2), which were confirmed by FISH." (PMID 32193378, 2020). "CD274, also known as PD-L1, was found to have high expression on the surface of various tumor cells, involving the development of tumors and affecting response to ICIs’ treatment and clinical outcomes." (PMID 33585244, 2020). "Tumor cells expressing Programmed cell death 1 ligand 1 (PD-L1, also known as CD274) bind the T-cell receptor PD-1, which suppresses the immune response and helps tumor cells to survive." (PMID 32854222, 2020). "Programmed death-ligand 1 (PD-L1) is a transmembrane protein encoded by the CD274 gene, located on chromosome 9, and is expressed by antigen presenting cells (APCs) and tumor cells." (PMID 32659961, 2020). "Taken together, these analyses suggest that the activation of CD274 gene expression in tumor-infiltrating macrophages depends primarily on the IRE1α pathway." (PMID 32520957, 2020). "HIF-1α directly binds the hypoxia-response element (HRE) in the CD274 proximal promoter, inducing PD-L1 expression in myeloid-derived suppressor cells (MDSCs) and tumor cells." (PMID 33114576, 2020). "For example, inhibition of the programmed cell death 1 (PCDC1/PD-1)/CD274 molecule (CD274/PD-L1) immune checkpoint using antibodies against PD-1 rescues effector T cell function, which permits T cells to maintain their tumor cell-killing function." (PMID 32346613, 2020). "Amongst the differentially expressed genes, CD274 (PD‐L1) was downregulated in the Cx3cr1‐Rheb1Δ/Δ compared to Rheb1fl/fl GL261 tumours, further highlighting a reduced level of T‐cell inhibition via checkpoint inhibitors in the TME (Fig EV3C)." (PMID 32567735, 2020). "Subsequent research proved that MLL1 catalyzed the formation of H3K4me3 after enrichment in the CD274 promoter, and it activates the expression of PD-L1 in tumor cells and leads to drug resistance." (PMID 32859239, 2020). "High PD-L1 expression and amplification of CD274 (encoding PD-L1) have been found in most TNBC and, along with the presence of tumor-infiltrating lymphocytes (TILs), has been shown to influence TNBC prognosis." (PMID 32892748, 2020). "Tumor patients with high CD274 expression levels of antigen-presenting cells in blood rarely responded to checkpoint inhibitor therapy." (PMID 33066260, 2020). "PD-L1, also known as CD274 and B7-H1, is a transmembrane protein commonly expressed on the surface of antigen presenting cells and tumor cells." (PMID 31507611, 2019). "Different subtypes were notable for particular molecular pathogenetic features; for example, EBV-positive tumours harboured recurrent PIK3CA mutations, along with amplifications involving JAK2, CD274 (encoding PD-L1) and PDCD1LG2 (encoding PD-L2)." (PMID 31790410, 2019). "Programmed cell death ligand 1 (PD‐L1, B7‐H1, CD274) is a transmembrane protein that is widely expressed on antigen‐presenting and other immune cells, and is unregulated on tumor cells from a broad range of cancer types." (PMID 31090214, 2019). "Addition of PDL1 (CD274) to the gene signature interrogated, drastically reduced the benefit of a higher infiltration in the tumor of CD8+CD69+ cells." (PMID 31214178, 2019). "In vitro flow cytometry data proved that CD47 and CD274 were overexpressed on the tested mouse tumor cell lines." (PMID 30872703, 2019).
tumor (continued). "In the reactive astrocytes from the tumor we identified an increased expression of immune associated genes such as CHI3L1, HLA-DRA, CD274, HLA-DRB3, CD37, as well as genes that contributed to proliferation (MKI67, ANXA2) and complement components (C1S, C1R)." (PMID 31186414, 2019). "Through coordination blockade the expression of CD47 and CD274 in tumor, the immune system can maintain the high quality of T cells and NK cells in vivo and prevent the immune escape of CTCs." (PMID 30872703, 2019). "The simultaneous blockade on both CD47 and CD274 checkpoints inhibited tumor growth and CTCs metastasis more potently than a single antibody inhibition or blank control on 4T1 tumor mouse model in vivo." (PMID 30872703, 2019). "We found that the expressions of all genes were higher in tumor tissues than corresponding normal tissues (P < 0.05) except for CD274 (PD-L1)." (PMID 31783776, 2019). "Together, these observations indicate CD274-L2A as the predominant source of sPD-L1, at least in the majority of tumour and healthy samples." (PMID 31729316, 2019). "We noted increased expression of PD-L1 (CD274) in solid tumors, consistent with adaptive immune resistance, as well as increased expression of PD-1 on tumor-specific CD8+ TALS following MIS416 Vax + MRB-OVA." (PMID 31315674, 2019). "In our previous gene expression profiling study, we observed upregulation of PD-ligand 1 (PD-L1, also known as CD274) mRNA in tumor compared to control tissues (GEO database GSE90597)." (PMID 30935402, 2019). "FFPE sections were macrodissected to enrich for tumor for quantitative assessment of CD274 (PD-L1), PDCD1LG2 (PD-L2), CD8A, and IRF1 by RT-qPCR multiplex mRNA panel." (PMID 31533832, 2019). "During tumor progression, there was a decrease in Cd274 (PD-L1)hi alveolar macrophages as assessed by RNA-Seq and a reciprocal increase in recruited monocytes and macrophages which expressed low to intermediate levels of Cd274." (PMID 31133614, 2019). "Expression of cytotoxic T-cell marker CTLA4 varied widely between patients, whereas expression of PD-1 (PDCD1) was uniformly low and tumor cell marker PD-L1 (CD274) was only moderately expressed." (PMID 30881919, 2019). "Collectively, our results revealed that the involvement of HFE and CD274 and their related molecules in acute phase liver graft injury and their concurrent involvement in post-transplant tumor recurrence." (PMID 29642405, 2018). "In contrary to HFE, we have demonstrated a high intragraft gene expression level of CD274 from recipients with post-transplant tumor recurrence." (PMID 29642405, 2018). "Its ligand, Programmed Death Receptor Ligand 1 (PD-L1, or B7-H1 or CD274), is expressed on tumor cells, macrophages, T cells and certain other cell types, and the interaction of these two molecules negatively regulates immune responses." (PMID 29535806, 2018). "Considering PD-1 ligand 1 (PD-L1, or CD274) is an important co-inhibitor for the immune inhibitory effect of PD-1, we further analyzed PD-L1 expression in tumor cells with PD-1 and other PD-1 relative immune profile." (PMID 30607140, 2018). "The CD274 promoter contains two interferon regulatory factor-1 (IRF-1) binding sites, and previous work has shown that type 1 and type 2 interferons (IFN) induce PD-L1 expression on T cells, B cells, endothelial cells, epithelial cells, and tumor cells." (PMID 29844327, 2018). "Although tumour PD‐L1 (CD274) expression had been used as a predictive biomarker in checkpoint immunotherapy targeting the PD1/PD‐L1 axis in various cancers, the regulation of PD‐L1 (CD274) expression is unclear." (PMID 29575535, 2018). "Functionally, T cells express PD-1 that, interacting with its ligands PD-L1 or PD-L2 (B7-H1/CD274 or B7-DC/CD273) on tumor cells, induces a tolerance state of tumor infiltrating T lymphocytes that are less capable of carrying out antitumor immunity." (PMID 29371600, 2018).
tumor (continued). "CD274, also known as PDL1, and PDCD1LG2 takes part in PD-1/PD-L1, PD-L2 pathway, which is involved in anti-tumor immune response." (PMID 29721214, 2018). "A prominent target that contributes to tumor cell evasion is the immune checkpoint programmed death ligand 1 (PD-L1), also referred to as B7-H1 or CD274." (PMID 29438316, 2018). "Doxorubicin treated tumours showed significantly higher expression of Cxcl10, Cd274, Isg15, Psmb9 and Calr." (PMID 30400822, 2018). "For example, the combined effect of the protein PD-L1 (CD274) on tumor cells and the protein PD-1 (CD279) on T cells prevents the T cells from killing tumor cells." (PMID 31294239, 2018). "RAS-MEK signaling upstream of p38-MAPK mediates tumor cell intrinsic expression of PD-L1, partly by supressing ZFP36-dependent CD274 mRNA decay, and promotes tumor-immune evasion." (PMID 29875770, 2018). "The tumor-related function of CD274 can also help to explain for its high intragraft gene expression level in transplant recipients with tumor recurrence as observed in this study." (PMID 29642405, 2018). "PD-1 interacts with the ligand, programmed death ligand 1 (CD274), expressed on tumour as well as other immune cells, to inhibit T-cell activation and cytokine production, eventually leading to tumour immune evasion." (PMID 28886030, 2017). "PD-L1 (also termed B7-H1 or CD274) is highly expressed in a number of tumor types and is recognized as a strong prognostic factor for affected patients." (PMID 28522811, 2017). "Immune checkpoint molecules, programmed death-1 receptor (PD-1, CD279) and programmed death ligand 1 (PD-L1, B7-H1 or CD274) play an important role in tumor immune escape." (PMID 28451792, 2017). "PD1 interacts with 2 ligands: PD-L1 (CD 274), expressed on the cell surface of activated lymphocytes (T, B and NK), peripheral tissues and organs, and to a greater extent by tumor cells, and PD-L2, expressed primarily by macrophages and dendritic cells." (PMID 28635639, 2017). "Our data extend the molecular understanding of the regulation of PD-L1 expression in cancer and highlight druggable targets to enhance anti-tumor immunity in tumors that are wild-type for the CD274 3′ UTR." (PMID 29246442, 2017). "The increased expression of CD274 (PD-L1) portends an additional resistance mechanism to immunotherapy in this sub population of tumor cells." (PMID 29156825, 2017). "In the series under investigation, promoter methylation of CD274 (mCD274) significantly correlated with mPDCD1 in tumor samples (r = 0.123; p = 0.005; n = 527)." (PMID 28487502, 2017). "A CD274 (PD-L1), a major molecular regulator of tumor immune escape, inhibits T cell-mediated immune attack by binding to the PD-1 receptor on tumor-specific T cells." (PMID 29108360, 2017). "The expression of the major PD-1 ligand PD-L1, encoded by CD274, is vital for anti-tumor immune tolerance, enabling the tumor cells to escape from T cell attacks." (PMID 28487502, 2017). "Programmed death-ligand 1 (PD-L1; also called B7-H1 or CD274), which is expressed on many cancer cells, is one of the most important inhibitory molecules that promote tumor immune escape." (PMID 29383103, 2017). "Specifically, cancer cells and MDSCs in the tumor microenvironment upregulate PD-L1 (CD274) to suppress anti-tumor immunity by inhibition of the T cell-mediated cytotoxicity." (PMID 28423491, 2017). "Sorted CD274-expressing M-MDSC from the peripheral blood of tumor-bearing mice showed a diminished expression of CD274 following treatment with miR-93 mimics." (PMID 28423491, 2017). "PD-L1 (also known as CD274 or B7 homolog 1 (B7-H1)) is abundantly expressed in various human cancers and can activate PD-1 signaling to induce T cell exhaustion in a tumor microenvironment." (PMID 28143527, 2017). "Another point of interest is the elevation in Notch2 and CD274 (PD-L1) expression in a subset of GD2-low tumor cells following P-selectin exposure." (PMID 29156825, 2017).
tumor (continued). "We chose these two genes to represent both a targetable alteration on the tumor cell (CD274) as well as a targetable indicator of a tumor immune microenvironment (CTLA4)." (PMID 27683114, 2016). "Assuming that increased APOBEC expression would cause more mutations, we inferred that increased expression of APOBEC correlates with PD-L1(CD274, B7-H1) expression in both tumor and immune cells." (PMID 27283319, 2016). "In colorectal cancer, an immunoregulatory tumor environment and CD274 expression have been reported in microsatellite instable cancers (MSI)." (PMID 27683114, 2016). "For instance, the loss of function of PTEN or activation of PI3K/AKT/mTOR signaling can enhance the expression of CD274 in tumor cells, which further leads to the escape from the surveillance by the immune system." (PMID 27855694, 2016). "The treatment with CD274-blocking antibodies was reported to efficiently reduce the tumor burden and restore cytotoxicity activities of CD8+ T cells in a murine chronic lymphoblastic leukemia model." (PMID 27855694, 2016). "In line with that, while peripheral murine B and CLL cells constitutively express low levels of CD274, we detected increased CD274 levels on lymph node- or spleen-residing tumour cells." (PMID 25940792, 2015). "These recent findings strongly suggest a fundamental contribution of the PDCD1/CD274 pathway to CLL tumour escape strategies." (PMID 25940792, 2015). "CD274 is also selectively expressed by various cellular components in the tumor microenvironment, where it inhibits tumor-specific T-cell immunity by inducing T cell apoptosis and delaying rejection." (PMID 21978817, 2011). "Based on many studies, overexpression of CD274 in common cancers helps tumor progression contributing to evasion from immune surveillance." (PMID 19852844, 2009). "Tumor cells also evade immune surveillance by upregulating CD274." (PMID 41986305, 2026). "In the high-risk group, we observed a substantial upregulation of several immune-suppressive and regulatory molecules, including PD-L1 (CD274), CD276, TIM-3 (HAVCR2), LAG3, and TGFB1, all of which are associated with an immunosuppressive tumor microenvironment." (PMID 40959429, 2025). "In addition to LAG3, two other important checkpoint molecules expressed by tumor cells, namely, the PD-L1 ligand (CD274) and its paralog PDCD1LG2, were significantly decreased in the high-risk groups." (PMID 40302936, 2025). "Furthermore, critical radioresistance and maintenance genes, including Cd274 (PD-L1), play a role in immune checkpoint regulation and influence the post-radiation tumor microenvironment." (PMID 41282050, 2025). "PD‐L1 (B7‐H1, CD274) is a cell surface glycoprotein belonging to the B7 family that serves as a ligand for PD‐1, expressed on the surfaces of immune cells and various types of tumor cells." (PMID 40923331, 2025). "Importantly, mIHC confirmed an inverse spatial correlation between PSD3 and CD274 protein expression in tumor tissues, suggesting potential regulatory crosstalk relevant to immune evasion." (PMID 40895529, 2025). "Additionally, it activates immune evasion mechanisms, including PD-L1/PD-1 checkpoint pathways (CD274), and tumour microenvironment remodelling and cell invasion by regulating adhesion molecules and promoting EMT." (PMID 41007296, 2025). "Finally, Prima and colleagues showed that the COX-2/mPGES1/PGE2 pathway plays a role in regulating PD-L1 (programed death ligand-1, CD274) expression in tumor-infiltrating myeloid cells." (PMID 40028333, 2025). "The expression of DDC significantly correlates with an immunosuppressive tumor microenvironment, higher intra-tumoral heterogeneity, elevated expression of the immune checkpoint CD274, and possibly mediates malignant behaviors of ccRCC cells via the PI3K/Akt signaling pathway." (PMID 40255484, 2025).
tumor (continued). "We hypothesized that the Toe-Macs in NSCLC are pathogenic, in part due to enhanced expression of the key tumor-promoting factors NLRP3, IL-1β, TGF-β1, CCL2, IL-6, and PD-L1 (encoded by CD274)." (PMID 40794443, 2025). "A pan-cancer study of 283,050 patient samples from multiple tumor types found that CD274 (PD-L1) gene rearrangements may be important for ICI-prone cancers when other genomic alterations are present." (PMID 39941003, 2025). "In addition to prognostic relevance, our ROC curve analyses showed that PSD3, CD274, and TNFSF18 exhibit moderate to high diagnostic accuracy in distinguishing tumor tissues from normal controls." (PMID 40895529, 2025). "Cells in the dominant subcluster (Neu_0, Neu_1, Neu_2, and Neu_5) with high expression of Ccl3 and Cstb defined as tumor‐specific neutrophils, which were enriched in the NPs group and exert pro‐tumor effects with a similar expression pattern of Cd274, Vegfa, and Lgals3." (PMID 39761175, 2025). "Overexpression of MSL1 significantly increased BIRC3, an anti-apoptotic factor, and HLA-A, a class I HLA molecule associated with antigen presentation, suggesting that MSL1 modulates CD274-dependent downstream signaling, potentially affecting apoptosis and the tumor microenvironment." (PMID 41409271, 2025). "Moreover, increased expression of immune checkpoint molecules, such as PD-L1 (CD274) and PD-L2 (PDCD1LG2), in high-risk patients suggests enhanced tumor immune evasion." (PMID 41153362, 2025). "However, the decreased expression of CD274 on the tumour cell surface in the anti‐PD‐L1‐treated group was due to the effective blocking of the PD‐L1 antibody." (PMID 39754316, 2025). "Several additional transcripts, including EpCAM, CK19, NANOG, PROM1, TERT, CDH5, FAM83A, and PTHLH, as well as high expression levels of BCL2, CD274 (PD-L1), CDH1, EPCAM, FGFR1, FN1, KRT18, MET, and MUC1, have been linked to reduced survival and aggressive tumor biology in NSCLC." (PMID 41373464, 2025). "Also enriched were interferon alpha/beta signaling and generation of second messenger molecules, further underscoring CD274’s role in T cell activation and immune checkpoint dynamics within the tumor microenvironment." (PMID 40895529, 2025). "However, within the tumor microenvironment, CD274 expressed on tumor cells engages CD279 on immune cells, leading to phosphorylation of immunoreceptor tyrosine motifs, recruitment of SHP1/2, and inhibition of ZAP70 and PI3K signaling." (PMID 41409271, 2025). "However, during the process of immune evasion tumor cells increasingly display “don’t-eat-me” signals, i.e., phagocytosis checkpoints, like programmed cell death 1 ligand 1 (PD-L1, CD274), MHC-I, and CD47, to tune down anti-tumor immune responses." (PMID 40098954, 2025). "On the contrary, IRF2 has been shown to inhibit transcription of Cd274 on tumor cells." (PMID 40442146, 2025). "The expression of immunoregulatory genes (e.g., Cd274, Pdcd1lg2, Cd200) as well as genes associated with Th2 responses and IL‐4 signalling limited the ability of cDCs to prime CTL and Th1 responses, resulting in increased tumour burden in mice." (PMID 40878038, 2025). "Patients with high proportions of HLA‐DR+ tumor cells exhibited poorer outcomes (HR = 1.34, 95% CI: 1.01–1.78, p = 0.043), and this effect was even more pronounced when considering HLA‐DR+CD274+ double‐positive tumor cells (HR = 1.53, 95% CI: 1.24–1.89, p < 0.001)." (PMID 40464412, 2025). "Knockdown of ALKBH5 increased the enrichment of m6A nearby the stop codon and 3’UTR region of CD274 mRNA, thereby promoting the decay of CD274 mRNA in a YTHDF2-dependent manner, but ALKBH5 has minimal inhibitory effects on tumor cell PD-L1 expression at the translational level." (PMID 38365891, 2024). "Here, Gal-9 was firstly evidenced with much higher expression on the primary solid tumors than such as CD80/86 (B7) and PD-L1 (CD274) as well, which suggests that Gal-9 may be a key factor in inhibiting the anti-tumor immunity." (PMID 38366083, 2024).